EGFR (epidermal growth factor receptor)
Diseases named in the same sentence as EGFR in open-access papers (continued):
Sharing a sentence is not in itself a finding about the gene and the disease.
lung cancer (continued). "Therefore, this case highlights the importance of being vigilant about the rapid development of the tumor after delivery in pregnant patients with EGFR-mutation lung cancer and taking preventive measures to cope with various emergencies." (PMID 37916176, 2023). "In addition, hypoxia has also been shown to induce a quiescent state in a model of patient-derived primary lung cancer harboring activating EGFR mutation." (PMID 36701089, 2023). "Moreover, another study on human NSCLC cell lines, HCC827 and H1650, demonstrated that PPARγ agonists sensitize PTEN-deficient lung cancer cells to EGFR TKIs via autophagy induction." (PMID 37190124, 2023). "Besides, the prevalence of EGFR mutation in lung cancer patients in Taiwan is higher than that in the western population." (PMID 36925928, 2023). "However, brigatinib showed limited efficacy in a phase I/II study evaluating drug use against EGFR-mutated lung cancer: only two out of forty-two patients had demonstrated a partial response to the drug." (PMID 38201251, 2023). "However, thanks to the progress in medical drugs and radiotherapy technology, the median survival time of patients with brain metastasis from lung cancer with EGFR mutation has reached 25 months." (PMID 38099066, 2023). "Epidermal growth factor receptor (EGFR) mutations are the most common driver mutations in lung cancer, but EGFR exon 20 insertions (EGFR ex20ins) mutation belongs to one of the rare mutations, accounting for about 4%-10% of overall EGFR mutations, thus around 1.8% of advanced NSCLC patients." (PMID 36872053, 2023). "EGFR plays an essential physiological role in regulating the development of epithelial tissue and homeostasis and hence is also linked to tumorigenesis, including lung cancer, breast cancer, and glioblastoma." (PMID 37601068, 2023). "The level of lung cancer glucose metabolism is correlated with a variety of factors, such as glycolysis-related gene expression, tumor immune microenvironment, Ki-67 expression, epidermal growth factor receptor, and tumor protein 53 mutation, among others." (PMID 36765284, 2023). "Additionally, while cSNX1.3 had minimal effect on the H1975 cell line, which has an EGFR driver mutation in the kinase domain (T790M), it was as ineffective as Sapitinib in the A549 lung cancer line with wildtype EGFR." (PMID 36253541, 2023). "Thus, the combination of osimertinib and the HER2-specific ADC trastuzumab emtansine showed efficacy in overcoming resistance to osimertinib in EGFR-mutated lung cancer." (PMID 37894376, 2023). "Lung cancer patients with EGFR mutations can be treated with gefitinib or osimertinib." (PMID 37508387, 2023). "Mutations in the tyrosine kinase domain of EGFR may be seen in lung cancer, frequently linked to increased EGFR gene copy numbers." (PMID 37692610, 2023). "The reason may be that the EGFR gene mutation phenotype of lung cancer in China is very different from that in the western countries." (PMID 36619220, 2023). "Although Osimertinib, the third generation of EGFR-TKI, was employed to address lung cancer with the T790M mutation and has shown excellent effectiveness in this setting, the acquired resistance to the third generation of EGFR-TKI, which involves the cysteine residue at codon 797, has been observed." (PMID 36902280, 2023). "Air pollution, lung cancer incidence and EGFR mutation status could be estimated for 16 geographical regions in South Korea." (PMID 37020004, 2023). "In addition, activation of JAK-STAT signalling causes de novo drug resistance to an irreversible EGFR TKI (afatinib) in lung cancer patients with EGFR TL mutations." (PMID 36810913, 2023). "According to the trials LUX-lung 3 and LUX-Lung 6, afatinib outperformed traditional chemotherapy in stage IIIB or IV (7th edition of TNM) lung cancer adenocarcinoma with del19 EGFR mutation (pemetrexed-cisplatin in LUX-Lung 3 and gemcitabine-cisplatin in LUX-Lung 6, respectively)." (PMID 36900362, 2023).
lung cancer (continued). "However, all EGFR mutations identified in the cobas® EGFR Mutation Test v2 were also detected in the Oncomine Lung cfDNA Assay in 12 out of 16 patients with lung cancer." (PMID 37372399, 2023). "Another similar study showed that the ORR following first-line treatment with icotinib was 52.6% (95% CI = 43.1–61.9%) for 116 patients with advanced lung cancer of unknown pathological status who had EGFR-sensitizing mutations in their ctDNA." (PMID 36835972, 2023). "Three next‐generation sequencing (NGS) databases (GENIE, FoundationInsights and GuardantINFORM) were analyzed to estimate the frequency of exon 20 insertion (ex20ins) variants in epidermal growth factor receptor (EGFR)–mutant non‐small cell lung cancer (NSCLC)." (PMID 36269676, 2023). "Notably, all three lung cancer cases, including our own, exhibited amplification or mutation of the EGFR driver gene." (PMID 37916176, 2023). "However, acquired resistance to EGFR-TKIs and associated adverse events pose a significant obstacle to targeted lung cancer therapy." (PMID 37089959, 2023). "To evaluate the effects of old age and EGFR mutation on treatment outcomes and toxicity, we reviewed the medical records of 71 consecutive patients with inoperable early‐stage non‐small cell lung cancer (NSCLC) who received SABR at Taipei Veterans General Hospital between 2015 and 2021." (PMID 36653333, 2023). "A higher gene mutation rate was found in non-smoking young Asian female patients with lung adenocarcinoma, especially EGFR mutation, among which mutations in exon E19 and E21 represented the vast majority (87%) of all EGFR mutations in patients with lung cancer." (PMID 37124493, 2023). "First‐generation EGFR‐tyrosine kinase inhibitors (TKIs) gefitinib and erlotinib, second‐generation EGFR‐TKI afatinib and dacomitinib, and third‐generation EGFR‐TKI osimertinib are approved as first‐line treatment for advanced non‐small cell lung cancer (NSCLC) with activating EGFR mutations." (PMID 38140788, 2023). "To date, the appropriate epidermal growth factor receptor tyrosine kinase inhibitors (EGFR-TKIs) for patients aged ≥75 years with advanced EGFR mutation-positive, nonsmall cell lung cancer remain unknown." (PMID 37179737, 2023). "Preclinical data suggest that the combination of EGFR TKIs and MET TKIs may be a possible treatment option for EGFR mutation‐positive lung cancer with MET‐driven acquired resistance." (PMID 38077251, 2023). "In addition, we did not include patients with known actionable driver alterations such as those with EGFR mutation-positive lung cancer or HER2-positive breast cancer." (PMID 36923436, 2023). "Another factor that might increase incidence of EGFR-mutated lung cancer appears to be air pollution." (PMID 37894376, 2023). "Moreover, EMT enrichment has been found in both EGFR-mutated lung cancer and melanoma DTCs, which can further demonstrate that DTCs are plastic." (PMID 37483492, 2023). "It has been reported that TKI treatment indirectly induces phenotypic changes in CAFs, which could promote DTC survival through STAT3 activation in lung cancers with EGFR mutations." (PMID 37638338, 2023). "Next, we investigated whether 8PN can reduce cell proliferation of lung cancer cells with different EGFR mutation status, including TC1 cells (EGFR wild‐type), Bm7 cells (EGFR wild‐type), and H1650 cells (EGFR exon 19 deletion and PTEN mutant)." (PMID 37013960, 2023). "Treatment with tyrosine kinase inhibitors (TKIs) is strongly recommended for patients with advanced non–small cell lung cancer (NSCLC) harbouring epidermal growth factor receptor (EGFR) mutations that are sensitive to TKIs, such as exon 19 deletion (19-Del) and exon 21 L858R (21-L858R)." (PMID 37140694, 2023).
lung cancer (continued). "These TME features were used to develop a prediction model for survival benefit from EGFR TKI therapy in patients with lung adenocarcinoma and EGFR-sensitizing mutations in the Lung Cancer Mutation Consortium 1 (LCMC1) and validated in an independent LCMC2 cohort." (PMID 36647832, 2023). "A frequent driving gene in the development of lung cancer is EGFR gene mutation." (PMID 37390230, 2023). "The era of molecular-based targeted therapy in lung cancer can be said to have started with the identification of activating oncogenic mutations in the epidermal growth factor receptor (EGFR) in NSCLC and subsequent development of the tyrosine kinase inhibitor gefitinib as treatment." (PMID 38144524, 2023). "Moreover, clinical trials have revealed that aging is a risk factor for advanced lung cancer with EGFR mutant subtypes." (PMID 36945046, 2023). "EGFR is an oncogenic gene and its high EGFR expression is associated with lung cancer." (PMID 37928424, 2023). "As compared to smokers with lung cancer, EGFR mutations occur at a high frequency among LCNS patients, the majority of which can be treated with oral targeted EGFR tyrosine kinase inhibitors (TKIs), osimertinib, as a first line treatment for such patients in advanced stages of disease." (PMID 37653450, 2023). "Recently, even though immunotherapies and gene mutation therapies that specifically targeted lung cancer have demonstrated excellent therapeutic effects, acquired resistance to epidermal growth factor receptor (EGFR)-tyrosine kinase inhibitors (TKIs) is unavoidable." (PMID 36935493, 2023). "Moreover, the lung cancer group was divided into two subgroups: patients who harbored the EGFR mutation and lung cancer patients with wild-type EGFR." (PMID 38068296, 2023). "In addition, ECA was found to inhibit cell cycle progression and induce apoptosis in EGFR L858R/t790m-mutated lung cancer cells at a concentration of 75 μM." (PMID 37047688, 2023). "In light of these alarming statistics, and the lack of effective treatment options, a study was conducted to explore the potential of phytochemicals derived from Cannabis sativa L to treat breast and lung cancers caused by abnormal enzymatic activity of EGFR-TKD (PDB ID:1M17)." (PMID 37128337, 2023). "Compared with lung cancer, EGFR mutation hardly happens in breast cancer." (PMID 35822637, 2023). "The difference in carrier rates of EGFR mutations between early‐onset and late‐onset lung cancer cohorts is highly debatable according to a previous study, though the lower KRAS mutation carrier rate in early‐onset colorectal cancer is consistent with one previous report." (PMID 37610374, 2023). "KRAS and EGFR-targeted drugs were applied for lung cancer patients with specific mutations." (PMID 36756386, 2023). "We utilized LCOs derived from lung cancer that exhibited EGFR mutation." (PMID 37508518, 2023). "We first search by gene name ‘EGFR’ on the front page of the m6A-CAVar database, then filter the results and keep only records related to lung tissue, which retains a total of 10 cancer m6A-associated variants from two lung cancer types." (PMID 36096444, 2023). "This study was more clearly showed the effect of NF1 mutations on EGFR mutant lung cancer patients." (PMID 35702826, 2023). "The study describes an N-acylhydrazone derivative of LASSBio-1586, named LASSBio-1920, with potent in vitro cytotoxic activity, especially against HCT-116 cells (human colon cancer) and PC-9 cells (human lung cancer with overexpression of EGFR with L858R mutation)." (PMID 37111767, 2023). "The T790M mutation rate was high, confirming that bronchial wash-derived EVs can be usefully analysed to detect DNA EGFR mutations, thus implying that EV-DNA analysis may provide valuable information for the management and treatment of lung cancer." (PMID 37296932, 2023).
lung cancer (continued). "All patients with primary lung cancer had adenocarcinoma histology, 14 (56%) had a mutation in the epidermal growth factor receptor (EGFR) gene, four (16%) had rearrangements of the anaplastic lymphoma kinase (ALK) gene, and six (28%) did not have any common somatic mutation detected." (PMID 35770957, 2023). "The m6A-CAVar database can be used to explore the role of m6A variants of EGFR in lung cancers." (PMID 36096444, 2023). "Air pollution, lung cancer incidence and EGFR mutation status could be estimated for 12 standard geographical regions in Taiwan." (PMID 37020004, 2023). "By performing in vitro assays on mutated (H1650 and PC-9) and wild-type (H1299) EGFR lung cancer cell lines, they showed that EGFR promoter hypermethylation enhanced the antitumor effect of TKI gefitinib and modulated the expression of EGFR both at transcript and protein level." (PMID 37152062, 2023). "The epidermal growth factor receptor (EGFR) gene has been found mutated in about 15% of Caucasian patients, and up to 50% or more in Asian patients with lung adenocarcinomas, and its driver mutations were the first ones to be targeted in lung cancer." (PMID 37047382, 2023). "For this reason, the Japan Lung Cancer Society guidelines for lung cancer treatment recommend osimertinib for use as the primary treatment for patients with advanced nonsmall cell lung cancer, with performance status 0-1 and common mutations of the EGFR gene." (PMID 37179737, 2023). "This case–control study aimed to investigate the potential association between ACE1 rs4646994 polymorphism and lung cancer risk in Chinese patients with pulmonary nodules, and whether this association is related to lung cancer histology and EGFR mutation." (PMID 37371643, 2023). "Exosomal RNA can be used as a biomarker for EGFR mutations in lung cancer." (PMID 37122754, 2023). "Lung cancers harboring EGFR mutations typically exhibit a positive response to EGFR TKIs." (PMID 37569564, 2023). "EGFR-mutated lung cancer patients responding well to TKIs eventually develop resistance." (PMID 36717865, 2023). "Notably, lung carcinoma presents the highest mutation in the region of EGFR protein tyrosine kinase (712–968 aa) followed by glioblastoma and melanoma (approximately 6% for both)." (PMID 37333807, 2023). "This budget may double in the case of NSCLC analysis, because lung carcinomas have to be additionally tested for EGFR, BRAF, KRAS, MET, and HER2 mutations as well as ALK, ROS1, and RET translocations." (PMID 37762506, 2023). "NSCLC cases harbouring EGFR driver mutations represent 10 - 20% of all lung cancer cases in Europe." (PMID 37465107, 2023). "Substantial breakthrough discoveries, including the identification of lung cancer–specific oncogenic drivers (e.g., EGFR mutations, EML4-ALK fusion genes) and the development of molecular inhibitors of these pathogenic factors, have improved outcomes for patients with advanced-stage lung cancer." (PMID 35166243, 2022). "Gefitinib is the good choice for the initial start of the EGFR mutated lung cancer treatment, although 50% of lung cell carcinomas showed resistance to gefitinib at the time of 7–12 months of treatment through mutations L858R and T790M and indicated the upregulation of EGFR activity." (PMID 36457709, 2022). "Therefore, this review comprehensively describes the dysregulation of ncRNAs in EGFR TKI-resistant lung cancer and its underlying mechanisms." (PMID 36139582, 2022). "However, EGFR inhibitors improved survival for only the small subset of lung cancer patients having tumors that harbor EGFR mutations." (PMID 36359830, 2022). "An EGFR mutation was detected in 18 lung cancers and 24 BMs." (PMID 35912248, 2022). "Among the detected alternations, the eight-major driver mutations of lung cancer (EGFR, ALK, ERBB2, MET, RET, ROS1, BRAF, and KRAS) could be found in 14 out of 17 (82.4%) patients using both surgical and CNB specimens." (PMID 36224661, 2022).
lung cancer (continued). "Fulvestrant can inhibit ER-related biological process, but concomitantly activate GPER1, which in turn transactivated EGFR causing cell proliferation, invasion and migration, which were demonstrated in breast, endometrial, ovarian, and recently in lung cancers." (PMID 35664735, 2022). "Previous studies have shown that E7050 may overcome HGF-induced resistance in lung cancer cells carrying epidermal growth factor receptor (EGFR) mutations by blocking the Met/Gab1/PI3K/Akt signaling pathway." (PMID 36499211, 2022). "The treatment options for epidermal growth factor receptor (EGFR)‐mutated non‐small cell lung cancer (NSCLC) with brain metastases (BMs) include EGFR‐tyrosine kinase inhibitors (TKIs), stereotactic radiosurgery (SRS), whole‐brain radiotherapy, brain surgery, and antiangiogenesis therapy." (PMID 35394114, 2022). "Lung cancer patients with a higher expression of EGFR have a higher mortality risk." (PMID 34766737, 2022). "Therefore, this study aimed to explore a supplementary method based on STMs to reveal the molecular features of EGFR‐mutated lung cancer during targeted therapy." (PMID 35543090, 2022). "However, the underlying mechanism of EGFR TKIs resistance in lung cancer is excursive, and the potential role of CAFs in lung cancer remains controversial." (PMID 35831824, 2022). "Furthermore, the overall mutational burden in EGFR-mut lung cancer is significantly smaller than EGFR WT lung cancers, indicating a molecularly more homogeneous intra-tumoral population." (PMID 35061724, 2022). "Thus, P3H4 represents a potential target in patients with lung cancer overexpressing EGFR mutations." (PMID 35805016, 2022). "Novel EGFRL858R/T790M selective inhibitors XTF-262 and EGFRT790M/C797S selective inhibitors EAI001 were also utilized to synthesis PROTAC 14o and DDC-01-163, respectively, which exhibited anti-proliferative activities in lung cancer cells with corresponding EGFR-mutations." (PMID 35410300, 2022). "In addition, the randomized ADAURA trial also showed a significant benefit from receiving osimertinib as adjuvant therapy after resection of stage IB-IIIA lung cancer with typical EGFR mutations." (PMID 36508072, 2022). "However, resistance to EGFR-TKIs is inevitable in the majority of EGFR-mutated lung cancer patients." (PMID 36033496, 2022). "However, in association with some lung cancers, mutations in epidermal growth factor receptor (EGFR) have been reported." (PMID 35607306, 2022). "Gefitinib (GF) is the first-choice drug for EGFR mutated lung cancer." (PMID 35813479, 2022). "Therefore, we aim to predict molecular features of EGFR‐mutated lung cancer, including the emergence of secondary EGFR‐T790M mutation and the clearance of EGFR ctDNA, by dynamically monitoring STMs during targeted therapy." (PMID 35543090, 2022). "In treatment-naïve lung cancer, oncogenic driver mutations, such as epidermal growth factor receptor (EGFR), Kirsten rat sarcoma virus (KRAS), BRAF, anaplastic lymphoma kinase (ALK), and ROS1, typically occur as trunk mutations with little intratumoral heterogeneity." (PMID 35008406, 2022). "EGFR-dedicated therapies with TKIs, such as afatinib and erlotinib, are currently used as first- and second-line lung cancer treatments, improving objective response rates and progression-free survival compared to cytotoxic therapy for patients with mutated EGFR." (PMID 35330479, 2022). "In our research, early lung cancer patients displayed a higher EGFR gene mutation frequency, which may be related to the varying clinical stages of lung cancer patients in the different studies." (PMID 35606799, 2022). "FAM188B prevented EGFR from degrading to cause lung cancer cells to re-adhere to the ECM." (PMID 36230714, 2022). "In addition, mutation of epidermal growth factor receptor (EGFR), which is considered one of the characteristics of lung cancer, also leads to the increased biogenesis and secretion of TDEs91." (PMID 36117219, 2022).